GFAP (glial fibrillary acidic protein)
Diseases named in the same sentence as GFAP in open-access papers (continued):
Sharing a sentence is not in itself a finding about the gene and the disease.
Stroke (continued). "In the late stage of stroke, astrocytes become hypertrophic and overexpress glial fibrillary acidic protein (GFAP)." (PMID 37464832, 2023). "Among the biomarkers that distinguish these two types of strokes, GFAP appears to be the most studied." (PMID 37511304, 2023). "Our objective was to investigate the ability of GFAP and PreSS to identify stroke subgroups in an unselected patient cohort with suspected stroke." (PMID 36604741, 2023). "In a review that included four studies with data from 340 patients, GFAP blood levels were significantly elevated in ICH compared to AIS patients, while in both stroke subtypes, the GFAP concentrations correlated with stroke severity." (PMID 37483444, 2023). "We also made a preliminary synthesis of the temporal change of GFAP within 24 h after stroke onset for the first time and synthesised summary sensitivity, specificity, and AUCs of GFAP in differentiating HS and IS according to different time points." (PMID 37762122, 2023). "A decision tree with PreSS and GFAP combined, first identified patients with a low probability of stroke." (PMID 36604741, 2023). "We compared relative abundance of each of these proteins in peri-infarct cortex between control and GFAP-TK + GCV mice at 28 days post-stroke to evaluate production of these factors by SVZ-derived cells relative to other cell types." (PMID 37816732, 2023). "For RBP4 values > 61 mcg/mL and GFAP < 0.07 ng/mL, the specificity in discerning between the two subtypes of Stroke is 100%." (PMID 37511304, 2023). "GFAP is an intermediate filament found exclusively in astrocytes; the differential levels of GFAP between IS and HS in the hyperacute phase of stroke shown in this study validate previous reports." (PMID 37685295, 2023). "Overall, their analysis indicated a higher GFAP+ area and more reactive astrocyte morphology following stroke." (PMID 37760829, 2023). "In contrast to our immunohistochemical analysis of the brains at 72 h post stroke, at 24 h post stroke, the expression of CD11b and GFAP genes were upregulated in the striatal and cortical core but not in the penumbra in the ischaemic hemisphere of all groups." (PMID 37957163, 2023). "In contrast, the cell destruction process evolves slower in patients presented with an ischemic stroke, thus leading to a delayed release of GFAP (typically between 6–12 h poststroke) and differentiating between the two main types of stroke." (PMID 36278689, 2022). "When a stroke occurs, both the destruction of glial brain cells and the disruption of the blood–brain barrier result in the release of great amounts of GFAP into the bloodstream, within minutes in case of ICH." (PMID 36278689, 2022). "Of note, the administration of Reelin or PLGA‐PEG in combination with NSCs can significantly reduce the number of recruited astrocytes (GFAP+ cells) in the periphery and inside the necrotic sites compared to the control stroke group." (PMID 35111956, 2022). "Although the GFAP expression in the stroke brain tissue was reduced by the transplantation of ahNSCs, it increased significantly in the analysis of the transcriptome of primary cortical neurons." (PMID 36446389, 2022). "Our data revealed that Iba1+ microglia and GFAP+ astrocytes were significantly active across the hippocampus’s focal area in the TI-induced stroke group, in comparison with those of the OLNZ treatment and sham groups." (PMID 36139770, 2022). "In this study, we found that astrocyte-specific deletion of Nhe1 not only attenuated Lcn2 gene and protein expression in GFAP+ astrocytes but also reduced stroke-induced neurodegeneration." (PMID 35440572, 2022). "To assess whether stroke outcomes could be improved by elevating astrocytic miR-20a-3p, we created a tetracycline (Tet)-induced recombinant adeno-associated virus (rAAV) construct where miR-20a-3p was located downstream a glial fibrillary acidic protein promoter." (PMID 34570349, 2022).
Stroke (continued). "Blood tau and glial fibrillary acidic protein levels peaked at 24–72 h and were lower at 3 months after stroke, whereas blood NfL levels continued to increase at 3 months, which makes it a promising biomarker for prognostic prediction after stroke." (PMID 35875791, 2022). "To determine the effects of cTBS treatment on gliogenesis after PT stroke, we co-stained for BrdU/Iba1 and BrdU/GFAP to identify newborn microglial and astroglial cells, respectively." (PMID 35966576, 2022). "In the stroke mouse model, glial fibrillary acidic protein (GFAP)+ astrocytes and CD4+ T cells, especially Tregs, are accumulated at the ischemic injury site at 14 days after MCAO, and this stockpile of astrocytes significantly increased upon Tregs-depletion." (PMID 35844606, 2022). "We found that, in the infarcted hemisphere, GFAP levels tended to be more pronounced in obese mice undergoing stroke." (PMID 35624723, 2022). "In rodent stroke, LCN2 deficiency reduced infarct volumes, and double-immunofluorescence staining identified GFAP+ astrocytes as the predominant cellular source of LCN2 in the penumbra 24 h after stroke." (PMID 35384588, 2022). "We therefore developed a model of secondary stroke, where photothrombotic stroke was induced in one hemisphere, mice were treated with PHP.GFAP-IL-2 or control, and then 14 d later photothrombotic stroke was induced in the opposite hemisphere." (PMID 35618831, 2022). "As expected, by day 4, GFAP positive cells were significantly increased in the stroke penumbra of control animals, beyond the mean number in the 10-1 group or contralateral normal side." (PMID 36533127, 2022). "Other biomarkers are studied in the stroke context: GFAP and Tau levels increase after stroke and are correlated with lesion volume and the NIHSS clinical score used for diagnosis and severity assessment." (PMID 36389064, 2022). "Expression of astrocyte-specific glial fibrillary acidic protein (GFAP) was evaluated as a marker of astrogliosis in the stroke penumbra." (PMID 36533127, 2022). "After a brain injury such as a stroke, astrocytes are characterized by a strong proliferation and concomitant expression of the structural protein GFAP." (PMID 35454177, 2022). "Quantitative GFAP analysis showed that GFAP expression at 4 days post-injury was significantly decreased in the stroke penumbra of 10-1 group as compared to controls, suggesting an attenuation in astrogliosis (Yang and Wang, 2015)." (PMID 36533127, 2022). "More specifically, it was shown that serum GFAP concentration early after ischemic stroke onset correlates well with ischemic lesion size and clinical severity among stroke survivors and appears to be a useful biomarker of poor prognosis in the case of AIS." (PMID 36278689, 2022). "Combinations of D-dimer and GFAP with a number of stroke severity scales increased the number of true positives, while reducing false positives due to hemorrhage, as compared to stroke scales alone (p-value < 0.001)." (PMID 34206615, 2021). "In line with the results obtained using the derivation cohort, the combination of D-dimer and GFAP with any stroke severity scale increased the accuracy for LVO detection, when compared to stroke scales alone." (PMID 34206615, 2021). "Overall, the addition of D-dimer and GFAP to stroke scales allowed us to increase the number of true positives, while reducing the number of false positives due to hemorrhage." (PMID 34206615, 2021). "Western blot analysis of changes in GFAP within the CST indicated that stroke increased GFAP expression in the CST (sham FC = 1 vs. stroke FC = 1.305, p < 0.05)." (PMID 34206635, 2021). "Critically, our findings indicate that combining D-dimer and GFAP with stroke severity scales has the potential to provide the level of diagnostic performance needed to safely triage LVO patients." (PMID 34206615, 2021).
Stroke (continued). "In line with the MRI, at 4 weeks post stroke, the lesion area determined with GFAP immunohistochemistry was 2.5 times larger in the large compared with the small strokes group (p < 0.001)." (PMID 32166716, 2021). "This corresponded with an increase in the number of GFAP and Iba-1 positive cells in stroke animals compared to sham animals (F = 108.5, p < 0.001 and F = 72.68, p < 0.001, respectively)." (PMID 33841293, 2021). "The lesion size and location at 4 weeks post stroke were quantitatively validated by immunohistochemistry of GFAP related to astrogliosis and the glial scar." (PMID 32166716, 2021). "Stroke induced a significant increase in both GFAP and Iba-1 immunoreactivity relative to sham animals (F = 55.06, p < 0.001 and F = 31.72, p < 0.001, respectively)." (PMID 33841293, 2021). "We observed that NR2 peptide (antibody against the NR2 fragment) and glial fibrillary acidic protein (GFAP) are brain-specific markers related to stroke." (PMID 34122297, 2021). "But for the two patients who had a stroke and one patient who died, the serum concentrations of GFAP and S100B increased continuously even at the 30-day follow-up after CAS." (PMID 34381130, 2021). "GFAP expression in the CC: Both CC regions (medial and lateral) exhibited stroke-induced increases in GFAP expression." (PMID 34206635, 2021). "In order to explore how aging influences astrogliosis in the thalamus following stroke, we quantified activated astrocytes in the thalamus by GFAP immunostaining." (PMID 34131204, 2021). "The final lesion size was determined using GFAP immunostaining, an established method in photothrombotic stroke research, to visualize activated astrocytes surrounding the necrotic stroke core as glial scar." (PMID 32166716, 2021). "Aged mice irrespective of their predisposing inflammatory status showed significantly increased level of astrocytic GFAP immunoreactivity in the PI‐area compared to young vehicle or LPS‐treated mice at 24 h after stroke." (PMID 33369048, 2021). "Blood flow was significantly diminished in GFAP-TK+GCV mice relative to controls on days 7–14 post-stroke." (PMID 33910014, 2021). "A major indicator of gliosis is an increase in the expression of glial fibrillary acidic protein (GFAP) by astrocytes, observed in stroke as well as AD models." (PMID 34867298, 2021). "We and others previously showed that brain-derived neuronal and glial markers, such as neurofilament light-chain (NF-L) and glial fibrillary acidic protein (GFAP), can be predictive biomarkers for stroke severity on admission and functional outcome." (PMID 33918875, 2021). "In our work, glial cell activation was assessed at 24-h and 30 days after stroke using GFAP (glial fibrillary acidic protein) as a marker of astrocytes and CD11b for microglia/macrophage activation." (PMID 34408211, 2021). "After stroke, astrocytes undergo many morphological changes to form a glial scar; these reactive astrocytes increasingly express GFAP, and this is used as a measure to determine the number and or size of the astrocytes." (PMID 33801560, 2021). "We combined D-dimer and GFAP with each stroke severity scale into multivariable logistic regression models." (PMID 34206615, 2021). "The GFAP immunoreactivity, normalized to the respective sham group, was highly increased in the infarcted ipsilateral striatum 8 weeks after stroke and was comparable between the dietary groups." (PMID 34937562, 2021). "Focal ischemic stroke was induced in adult GFAP-Cre-Rosa-YFP mice that then received ND1 lentivirus injections into the peri-infarct region 7 days after stroke." (PMID 33841125, 2021). "GFAP protein expression in the stroke 1-day group was higher than that in the sham 1-day group (n = 5, p < 0.01)." (PMID 33642941, 2021). "Hypertrophic astrocytic processes and stellate morphology were highly evident in peri-infarct regions of both stroke mice by GFAP immunohistochemistry." (PMID 34046769, 2021).
Stroke (continued). "Previous work has shown that GFAP levels are elevated in hemorrhagic stroke patients, as compared to ischemic strokes, stroke mimics, and/or TIAs." (PMID 34206615, 2021). "Assessment of GFAP immunofluorescence 42 days post-stroke revealed extensive peri-infarct reactive astrogliosis." (PMID 33801560, 2021). "Our study demonstrates that, when measured with D-dimer, GFAP can significantly improve LVO identification by ruling out hemorrhagic patients whose clinical stroke scales often suggest the presence of LVOs." (PMID 34206615, 2021). "We used the number of GFAP+BrdU+ cells in peri-infarct cortex on day 21 post-stroke to confirm the near complete ablation of proliferating peri-infarct astrocytes in GFAP-TK+GCV mice, and large numbers in control mice." (PMID 33910014, 2021). "We found that the protein expression of GFAP increased one day after the stroke but decreased to normal levels after 7 days." (PMID 33642941, 2021). "As early as day 1 post-stroke, the dense immune-reactivity with anti-Iba1 as well as anti-GFAP antibody was detected around the ischemic core." (PMID 32264906, 2020). "In summary, GFAP cannot be considered a characteristic marker of only one type of stroke and is also activated in the course of traumatic brain injury." (PMID 31701356, 2020). "The highlight of the present study was that it demonstrated that plasma biomarkers, NfL and GFAP, had the ability to identify stroke or ICH events in CADASIL patients." (PMID 32321529, 2020). "In a rat stroke model, M4P co-localized with neuronal marker NeuN and endothelial marker vWF, whereas few GFAP positive astrocytes were stained by M4P in the ipsilateral hemisphere." (PMID 33195194, 2020). "BrdU was injected after stroke for 5 consecutive days to label dividing glial cells before injecting AAV GFAP::Cre and FLEX-mCherry or FLEX-NeuroD1-mCherry viruses." (PMID 33224952, 2020). "For example, morphological changes of IBA1+ microglia/macrophages and GFAP+ astrocytes following activation has been documented in many studies of neuroinflammation and stroke specifically." (PMID 33551749, 2020). "The time window of between 1 and 6 h after stroke onset is best for using GFAP to differentiate between intracerebral hemorrhage and ischemic stroke." (PMID 32266274, 2020). "The study will evaluate known stroke biomarkers, e.g. Glial Fibrillary Acidic Protein (GFAP) and NR2 peptide, and explore novel markers (during a discovery phase) via blood samples taken by EMS clinicians during transit." (PMID 32336270, 2020). "To investigate the NeuroD1 treatment effect, we performed a series of immunostaining including NeuN, GFAP, and Iba1 to understand the overall neuronal and glial morphology in the stroke areas." (PMID 33224952, 2020). "Decreased GFAP staining was observed in the ipsilateral striatum of both genotypes after stroke with a larger decrease in Cav-1 KO mice than WT mice at 72 h after stroke onset." (PMID 32523952, 2020). "Morphological analysis also revealed significant relationships between IBA1+, GFAP+, and NeuN+ areas with 1.8% of examined morphologies between these areas correlating pre-stroke and 10.2% correlating post-stroke." (PMID 33551749, 2020). "GFAP+ cells are astrocytes that also play an essential role in the neuro-inflammatory response to stroke." (PMID 32345303, 2020). "Cav-1 KO mice also had a lower degree of GFAP branching after stroke in the perilesional and contralateral cortex than WTs in agreement with our earlier work." (PMID 32523952, 2020). "Higher baseline NfL (HR 1.93, 95% CI 1.19–3.13) predicted any incident stroke, whereas higher GFAP (HR 2.80, 95% CI 1.21–6.53) predicted incident ICH." (PMID 32321529, 2020). "Under pathological conditions like stroke, glial fibrillary acidic protein (GFAP) which is an intermediate filament and a selective marker of astrocytes up regulates in reactive astrocytes." (PMID 32150581, 2020).
Stroke (continued). "There was a significant decrease (p<0.05) in GFAP+ cells in the peri-infarct area in the rGDF11 treated mice compared to vehicle-treated stroke mice, reflecting reduced astrogliosis after exogenous rGDF11 treatment." (PMID 32365331, 2020). "The extent of gliosis was determined using GFAP staining in vehicle and drNPC transplanted mice at 32 days post-stroke by measuring the maximal cortical GFAP+ area, which was strongly correlated (r = 0.89, n = 35, p < 0.001) to total gliosis volume per brain." (PMID 30747366, 2020). "In the TTC+ stroke mice, GFAP was increased in the thalamus (p = 0.0100) and hippocampus (p < 0.0001)." (PMID 31417355, 2019). "Immunohistochemistry revealed that there were similar numbers of CD45+ leukocytes, neutrophils (MPO+), T cells (CD3+), astrocytes (GFAP+) and microglia-macrophages in the ischemic hemisphere of WT compared with IL-37tg mice after stroke." (PMID 31061403, 2019). "When astrogliosis is attenuated by double knockout of GFAP and vimentin in mice that then underwent stroke of motor cortex, corticospinal axons only rarely crossed the midline and their length was significantly reduced compared to the axons in wild‐type mice." (PMID 31271523, 2019). "Glial fibrillary acidic protein was significantly increased in all investigated regions in the TTC− stroke mice compared to sham (infarct p = 0.0015; thalamus p < 0.0001; hippocampus p < 0.0001)." (PMID 31417355, 2019). "After stroke, traumatic brain injury and spinal cord injury, GFAP, and GFAP breakdown products have been found in CSF and serum." (PMID 31379804, 2019). "Injured cortex becomes hypertrophic in many types of CNS disorders such as stroke and neurotrauma, which is often accompanied with the upregulation of GFAP in astrocytes." (PMID 31142341, 2019). "Infarct size, neurological function, apoptotic cells and expression levels of Glial Fibrillary Acidic Protein (GFAP) were evaluated 1 week after stroke." (PMID 31031895, 2019). "SDF-1 was primarily localized to neurons and astrocyte either in brains of patients with stroke or normal brains, which were identified by staining for neuronal nuclei (NeuN) and GFAP-expressing astrocytes." (PMID 29896417, 2018). "The ipsilateral to contralateral ratio of the GFAP-positive area in the striatum increased over time, reaching a significant level only at day 7 post-stroke (464%)." (PMID 29884977, 2018). "Taken together, these findings seem to indicate that the extent of the ischemia-induced damage in GFAP-/-Vim-/- mice is highly dependent on the specific stroke model used." (PMID 29401502, 2018). "Our results showed that NT-1 can inhibit GFAP expression, reduce chemokine release, and promote recovery, partly through reducing astrocytes activation, which expands the role of NT-1 in stroke pathology." (PMID 30227858, 2018). "Astrocyte size and GFAP expression were decreased in brains of Ppp3cb KO mice following photothrombotic stroke or traumatic brain injury." (PMID 29422055, 2018). "At 7 days after dMCAO, WT and GFAP-/-Vim-/- mice were transplanted with 100 000 GFP-labeled hiPSC-NSPCs in the cortex adjacent the stroke lesion (within 1 mm from the lesion border)." (PMID 29401502, 2018). "In contrast, ISO-1-treated (1 mg/kg) rat showed the less GFAP-stained cell in the brain tissue after stroke." (PMID 29335619, 2018). "Further, PEG-IGF-I treatment increases GFAP expression when given early (3 hrs post-stroke), increases Synaptophysin expression and increases neurogenesis in young and aged." (PMID 28325900, 2017). "Serum GFAP levels are elevated in different pathologic conditions affecting the CNS, including stroke and tumor." (PMID 29383115, 2017). "Taken together, quantitative analysis of the GFP, GFAP, and nestin-positive cells revealed a significant increase in cell numbers starting at 3 days and peaking 7 days after stroke." (PMID 28253906, 2017).